FANCD2 (FA complementation group D2)
Diseases named in the same sentence as FANCD2 in open-access papers (continued):
Sharing a sentence is not in itself a finding about the gene and the disease.
lymph node metastasis (3 papers, 2020 to 2023). "It is confirmed that elevated FANCD2 was an independent prognostic factor, and was associated with lymph node metastasis, tumor size and stage in tumors." (PMID 37369808, 2023).
renal carcinoma (3 papers, 2018 to 2022). A carcinoma arising from the epithelium of the renal parenchyma or the renal pelvis. "Other gene mutations, such as FANCD2, FAT3, KDM6A, KDR, TET2, and TSC2, occurred twice in this MA cohort, which was quite different from other common types of renal carcinoma." (PMID 30111351, 2018).
renal cell carcinoma (3 papers, 2017 to 2023). "We therefore first performed western blotting for FANCD2 in VHL-deficient and VHLWT-complemented 786-O renal cell carcinoma cells after exposure to normoxia or hypoxia (<0.01% O2) for 24 and 48 h." (PMID 29435132, 2018). "In case of Caki‐1 renal cell carcinoma cells, cell proliferation/survival decreased after FANCD2 knockdown with FANCD2 siRNAs (siFD2#2 or siFD2#4) compared with control siRNA‐transfected cells (siControl) at the AICAR concentration of 0.12 mm in MTT assay." (PMID 28174693, 2017). "Furthermore, FANCD2 disturbance in normal fibroblasts and renal cell carcinoma (RCC) cells led to changes in AICAR‐induced cell cycle arrest and apoptosis." (PMID 28174693, 2017). "Furthermore, robust FANCD2 monoubiquitination was also observed after AICAR treatment of Caki‐1 renal cell carcinoma cells." (PMID 28174693, 2017). "Furthermore, FANCD2 repression enhanced cell death upon AICAR treatments in transformed fibroblasts and cell cycle arrest in the renal cell carcinoma cell line Caki‐1." (PMID 28174693, 2017).
rhabdomyosarcoma (3 papers, 2015 to 2018). A rare aggressive malignant mesenchymal neoplasm arising from skeletal muscle. "Co-localization of FoxF1 with FANCD2 was also observed in a subset of tumor cells located within cisplatin-treated rhabdomyosarcoma tumors." (PMID 26625197, 2016). "However, this does not exclude a role for mTOR-dependent regulation of Chk2 in the DNA damage response as a recent report shows that in response to DNA damage, mTORC1 through FANCD2 is required for ATM-Chk2 activation in rhabdomyosarcoma cells." (PMID 25460505, 2015).
sarcoma (3 papers, 2016 to 2023). A usually aggressive malignant neoplasm of the soft tissue or bone. "The tumor-inducing K14E7 Fancd2−/−, cell line had low levels of some markers of mesenchymal cells including osteoblasts (osteocalcin) and endothelial/sarcoma (Collagen IV)." (PMID 27637088, 2016).
squamous cell carcinoma (3 papers, 2014 to 2022). A carcinoma arising from squamous epithelial cells. "In experiments treating orthotopic tumors derived from the TC1 squamous cell carcinoma cell line (derived from C57BL/6J mice), single fraction or fractionated irradiation of mice with palpable tumors was successful in Fancd2−/−, heterozygote, and control Fancd2+/+ mice." (PMID 24596683, 2014).
adenoma (2 papers, 2022 to 2023). A neoplasm arising from the epithelium. "This study provides initial genetic evidence that the sex cord can be classified as a bona fide precursor to adenomas in Fancd2−/− mice." (PMID 37174061, 2023). "We show for the first time that the gene expression signature of the precursor lesion (sex cords) identified in young Fancd2−/− mice has significant similarities to a late-stage (adenoma) phenotype, including an increase in the expression of key epithelial markers." (PMID 37174061, 2023). "Once a tumour phenotype was established, a multiplex gene expression assay was used to determine a genetic link between the identified precursor lesion of the sex cords in ovaries of 3-month Fancd2−/− mice and the tubulostromal adenoma ovarian tumour phenotype in 1-year old Fancd2−/− mice." (PMID 37174061, 2023).
Alzheimer disease (2 papers, 2024). A progressive, neurodegenerative disease characterized by loss of function and death of nerve cells in several areas of the brain leading to loss of cognitive function such as memory and language. "Also relevant to our findings, a pair of SNPs in FANCD2 and FANC2DOS (rs1552244 & rs9849434) were among the top-25 hits from an early Alzheimer’s disease GWAS meta-analysis (albeit not replicated in more recent studies with larger Ns)." (PMID 38431614, 2024).
bone marrow failure syndrome (2 papers, 2020 to 2023). "Mutations in FANCD2, FANCI or FA core complex components cause the FA bone marrow failure syndrome." (PMID 32725171, 2020).
colorectal tumors (2 papers, 2015 to 2016). "Expression of Rad51C variants is associated with FANCD2 foci positive colorectal tumors and is associated with microsatellite stability in those tumors." (PMID 25669972, 2015). "Expression of the fusion gene is correlated to FANCD2 foci deficiency in those colorectal tumors." (PMID 27296891, 2016). "We analyzed FANCD2 foci status and Rad51C variants expression in colorectal tumors." (PMID 25669972, 2015). "Based on FATSI, 20 of 67 (30 %) colorectal tumors examined were defective for FANCD2 foci formation and 47 (70 %) were FANCD2 foci positive." (PMID 27296891, 2016). "Among 67 human colorectal tumors analyzed, there was a significant correlation between the presence of the fusion gene and lack of FANCD2 foci." (PMID 27296891, 2016).
Ewing sarcoma (2 papers, 2020 to 2025). A small round cell tumor that lacks morphologic, immunohistochemical, and electron microscopic evidence of neuroectodermal differentiation. "In particular, fusion-positive Ewing sarcoma cells (A673 and TC32) exhibit exquisite sensitivity to THZ531, a CDK12/13 inhibitor, resulting in the downregulation of the homologous recombination (HR) and DNA damage checkpoint genes, including BRCA1, ATR, FANCl, and FANCD2." (PMID 40760094, 2025).
Fanconi Anemia Complementation Group (2 papers, 2017 to 2020). "However it contains FANCD2 (Fanconi Anemia Complementation Group D2) which is involved in double-strand breaks DNA repair and the maintenance of chromosomal stability." (PMID 28650955, 2017).
Hereditary breast cancer (2 papers, 2014 to 2017). Breast carcinoma that has developed in relatives of patients with history of breast carcinoma. "In total, four of the recurrent mutations showed significant (TEX15 c.7253dupT and FANCD2 c.2715 + 1G > A) or borderline association (TEX15 c.8325G > A and RNF168 c.640_644del5) with hereditary breast cancer in the Northern Finnish cohort." (PMID 28386063, 2017). "In conclusion, our study suggests that a deletion of the VHL and FANCD2 gene may be associated with coexistence of VHL disease and hereditary breast cancer, but further studies are needed in this regard." (PMID 25093046, 2014).
karyomegalic interstitial nephritis (2 papers, 2021 to 2023). Any interstitial nephritis in which the cause of the disease is a mutation in the FAN1 gene. "Karyomegalic interstitial nephritis (KIN) is a genetic kidney disease caused by mutations in the FANCD2/FANCI-Associated Nuclease 1 (FAN1) gene on 15q13.3, which results in karyomegaly and fibrosis of kidney cells through the incomplete repair of DNA damage." (PMID 37759541, 2023).
Li-Fraumeni syndrome (2 papers, 2020 to 2021).
lung squamous cell carcinoma (2 papers, 2022 to 2023). "The results revealed that FANCD2 expression was significantly upregulated in LUAD and lung squamous cell carcinoma (LUSC) tissues than that in normal tissues." (PMID 35646059, 2022). "For example, USP1 deubiquitinates FANCD2/FANCI or PCNA to prevent the recruitment of interstrand crosslink repair proteins and translesion DNA polymerase to inhibit DNA repair; USP7 regulates lung squamous cell carcinoma cell proliferation through MEK/ERK signaling by deubiquitinates the Raf-1." (PMID 37107644, 2023).
microcephaly (2 papers, 2022 to 2024). A congenital or acquired developmental disorder in which the circumference of the head is smaller than normal for the person's age and sex. "Structural CNS anomalies have been associated with PVs in ID2 complex genes, microcephaly with PVs in FANCD1, FANCD2, FANCJ, ID2 complex, downstream genes, and hydrocephalus with FANCB genotype." (PMID 36091172, 2022).
ovarian tumors (2 papers, 2020 to 2023). "For the first time, this study demonstrates a genetic relationship between the sex cords and a late-stage ovarian tumour in Fancd2−/− mice, providing robust evidence that this is a precursor lesion in this animal model." (PMID 37174061, 2023).
plasma cell tumors (2 papers, 2015 to 2016). "The tumor-inducing K14E7 Fancd2−/− clone 1 cell line and the tumors induced by this cell line were positive for both immunoglobulin kappa and lambda light chains, consistent with a plasma cell tumor." (PMID 27637088, 2016).
rectal NETs (2 papers, 2023 to 2024). "Among neuroendocrine neoplasms of various locations, FANCD2 mutation was detected in rectal neuroendocrine neoplasms and intestinal NETs." (PMID 39768544, 2024).
serous carcinomas of the ovary (2 papers, 2012 to 2022). "Moderate FANCD2 staining was found in most (85%) stage I serous carcinomas of the ovary [Pejovic, unpublished data], while in this series we find that 40% of advanced serous carcinomas overexpress FANCD2." (PMID 22253870, 2012).
small cell lung carcinoma (2 papers, 2014 to 2021). Small cell lung cancer (SCLC) is a highly aggressive malignant neoplasm, accounting for 10-15% of lung cancer cases, characterized byrapid growth, and early metastasis. "Non-small cell lung cancer cell lines A549, H1299, and small cell H719, H792 were transduced with FANCD2-specific shRNA-expressing and puromycin-resistant lentiviral particles, or control shRNA lentiviral particles." (PMID 25566506, 2014).
acute lymphoblastic leukemia (1 paper, 2015). Leukemia with an acute onset, characterized by the presence of lymphoblasts in the bone marrow and the peripheral blood. "Also, the FancD2−/−/Aldh2−/− mice, which can no longer detoxify aldehydes by oxidizing them to carboxylic acids, present with severe phenotypes including the development of acute lymphoblastic leukemia (ALL) after three to six months." (PMID 25622253, 2015).
anaplastic astrocytoma (1 paper, 2014). "This patient was re-admitted in 2012 with biopsy proven transformation to grade III anaplastic astrocytoma from which we were again able to determine FANCD2 expression." (PMID 25071006, 2014).
astrocytomas (1 paper, 2021). "Furthermore, sequencing of three subependymal giant cell astrocytoma (SEGA)-like astrocytomas in NF1 mutant patients with ALT and intact ATRX have revealed genetic alterations in RECQL4, Fanconi anemia complementation group genes (FANCD2, FANCF, and FANCG), and SMARCAL1." (PMID 34069193, 2021).
behavioral disorder (1 paper, 2024). "For example, 33 of 47 FANCD2 target protein coding genes from the Blaize dataset are associated with the human phenotype (Monarch) mental or behavioral disorder biomarker (FDR 2.5 × 10− 21)." (PMID 39365306, 2024).
benign papillomas (1 paper, 2013). "In the tongue, we only observed four benign papillomas in K14E6E7/FancD2+/+ mice, whereas in the K14E6E7/FancD2-/- mice we observed three benign papillomas, four grade I carcinomas, and two grade II carcinomas." (PMID 24086435, 2013).
bladder tumour (1 paper, 2021). "Survival Cox analysis identified FANCD2 as a risk factor for bladder tumour prognosis in the present study (p = 0.021)." (PMID 34095228, 2021).
bowel cancer (1 paper, 2021). "While the germline alterations in certain susceptibility genes were also detected in the bowel cancer samples including FANCD2, CDH1, FLCN, MEN1, SDHB, and SLX4, which have been rarely reported in the Chinese population." (PMID 35154239, 2021). "In this case-control study, mutations in 8 genes (APC, ATM, MLH1, FANCD2, MSH3, MSH6, PMS1, and RAD51D) were found to be associated with bowel cancer and were present in 3.5% of patients with bowel cancer." (PMID 35154239, 2021).
brain tumours (1 paper, 2014). "Even with the caveat that this is a single case, taken together with our analyses of over 165 normal, benign schwannomas and brain tumours derived from multiple patients, our data reveal that FANCD2 expression is significantly associated with tumour grade." (PMID 25071006, 2014). "Even though we have determined that FANCD2 expression increases with brain tumour grade, it does not indicate if the FA pathway is active in these tumours and could contribute to chemotherapeutic resistance mechanisms." (PMID 25071006, 2014).
bronchogenic carcinoma (1 paper, 2008). A lung carcinoma arising from the bronchial epithelium. "To determine if neoplastic cells retained responsiveness to CSC, we measured the effects of CSC on FANCD2 expression in bronchogenic carcinoma cells (A549 and H292)." (PMID 18475298, 2008). "Furthermore, we found that bronchogenic carcinoma cells were still sensitive to CSC-induced FANCD2 downregulation and thus CIN, but were at least in part resistant to CSC-induced apoptosis." (PMID 18475298, 2008). "Finally, CSC downregulated FANCD2 in bronchogenic carcinoma cells, but these cells were partially resistant to CSC-induced toxicity." (PMID 18475298, 2008). "Cigarette smoke condensate also suppressed FANCD2 function and induced CIN in bronchogenic carcinoma cells, but these cells were resistant to CSC-induced apoptosis relative to normal airway epithelial cells." (PMID 18475298, 2008). "Thus, bronchogenic carcinoma cells (A549 and H292) do exhibit CSC-induced FANCD2 suppression, but have become partially resistant to CSC." (PMID 18475298, 2008). "Furthermore, FANCD2 suppression induced CIN in exposed normal and neoplastic epithelial cells; however, bronchogenic carcinoma cells were resistant to CSC-induced toxicity." (PMID 18475298, 2008).
cervical tumors (1 paper, 2014). "Increased protein levels of FANCD2, RAD51, BRCA1, and BRIP 1 (BACH1) in NCR compared to CR cervical tumors groups were confirmed on the validation set." (PMID 24708616, 2014). "Our results revealed an increased protein level of FANCD2, RAD51, BRCA1 and BRIP1 in the NCR compared to CR cervical tumor nuclei." (PMID 24708616, 2014). "We observed a significantly increased protein levels of FANCD2, BRCA1, RAD51 and BRIP1 in the nuclei of the NCR compared to the CR cervical tumors." (PMID 24708616, 2014).
cholangiocellular carcinomas (1 paper, 2010). "We assessed proximal and distal FA pathway function in 48 cell lines derived from gastric, pancreatic, colorectal, hepatocellular and cholangiocellular carcinomas applying assays for FANCD2 monoubiquitination and FANCD2/RAD51 focus formation." (PMID 20509860, 2010).
CMV infection (1 paper, 2026). "Here, we show that USP1, PCNA, and FANCD2, were relocalized to sites of vDNA synthesis during productive CMV infection in primary fibroblasts." (PMID 41533576, 2026). "While further work is required to define specific roles of FANCD2 in CMV infection, our data suggests the FA pathway is important for repair of the viral genome during replication." (PMID 41533576, 2026). "Taken together, these data are consistent with the hypothesis that UL138 influences the deubiquitylation of mUb–PCNA and mUb–FANCD2 in CMV infection." (PMID 41533576, 2026).
colorectal adenocarcinoma (1 paper, 2017). The most common type of colorectal carcinoma. "First, we attempted to recapitulate acetaldehyde sensitivity in human colorectal adenocarcinoma DLD1 cells in which we deleted FANCD2 gene using the CRISPR/Cas9 system." (PMID 28729482, 2017).
cystadenocarcinoma (1 paper, 2023). A malignant cystic epithelial neoplasm arising from the glandular epithelium. "Previously, we and others reported that Fancd2−/− mice develop multiple benign and malignant ovarian cancer phenotypes, including cystadenomas, cystadenocarcinomas, tubulostromal adenoma and adenocarcinomas, based on classifications defined by Mohr 2001." (PMID 37174061, 2023).
diabetes (1 paper, 2019). "For instance, the diabetes drug metformin, was found to improve hematopoiesis and to delay tumor formation in Fancd2−/− mice." (PMID 31219578, 2019).
dyskeratosis congenita (1 paper, 2023). Dyskeratosis congenita (DC) is a rare ectodermal dysplasia that often presents with the classic triad of nail dysplasia, skin pigmentary changes, and oral leukoplakia associated with a high risk of bone marrow failure (BMF) and cancer.
eye cancers (1 paper, 2024). "Additionally, other genes such as ATR, RAD18, and FANCD2 were the most frequently mutated in specific cancer types such as skin, kidney, and eye cancers, respectively." (PMID 39421870, 2024).
Hepatitis (1 paper, 2023). Inflammation of the liver. "Based on our study, we found that high expression of FANCD2 is associated with a higher TIDE score in Hepatitis B-related HCC." (PMID 37821996, 2023).